SNORA108 (small nucleolar RNA, H/ACA box 108)
Gene: Small nucleolar RNA gene on chromosome 18 (58,600,631 to 58,600,698, forward strand). Ensembl gene ENSG00000252284.
Homologues: Orthologues: chimpanzee SNORD28 (100% identical), pig SNORD28 (71% identical), tropical clawed frog SNORD28 (60% identical). Paralogues in human: SNORD28 (75% identical), SNORD28B (69% identical).